WNT10B (Wnt family member 10B)
Diseases named in the same sentence as WNT10B in open-access papers (continued):
Sharing a sentence is not in itself a finding about the gene and the disease.
cancer (continued). "Among the possible candidates, we further analyzed DNMT1, CCKBR, WNT10B, NOG and ROBO1, which are five genes whose functions have been associated with carcinogenesis or cancer development." (PMID 21205300, 2011). "In this case, one could speculate that cancer cells might exhibit dysfunctional Wnt10b signaling leading to impaired fork maintenance and repair resulting in elevated levels of chromosomal breaks and CIN." (PMID 40846632, 2025). "Thus, our results show that Wnt10b signaling regulates replication stress–induced chromosome missegregation and breakage, and hence is a determinant for broad genome instability in cancer cells." (PMID 40846632, 2025). "Wnt family member 10B (WNT10B) and mitogen-activated protein kinase kinase kinase 6 (MAP3K6) associated with progression-free survival in our analysis belong to widely studied and cancer related WNT and MAPK gene families." (PMID 36809527, 2023). "WNT10B is directly downstream of the cancer pathway gene WNT1 (~8 kb away)." (PMID 37756103, 2023). "Moreover, the expression level of WNT-10B correlated with the histological type of the cancer, FIGO stage, and lymphatic metastasis." (PMID 37176048, 2023). "In addition, as a H3-K4 methyltransferase, SMYD3 trans-activates many genes, including MMP-9, Bcl-xL, WNT10B, and Nkx2.8, all of which play critical roles in cancer development and/or progression." (PMID 32007952, 2020). "However, how Wnt10b affects the cancer cellular physiology by NSD1 alteration should be the subject of further investigation." (PMID 31727171, 2019). "The interaction between FGF, WNT10B and cancer growth may prove to be highly relevant to the pathogenesis of inflammation induced carcinogenesis in CCA." (PMID 23110045, 2012). "These target genes, including IGFBP1, WNT1, WNT10B, TGFB1, PCK1, and SLC2A3, are critical for cancer cell proliferation and metastasis." (PMID 42311859, 2026). "LINC00355 induces chemotherapy resistance in cancer cells by regulating five downstream genes, namely HMGA2, ABCB1, ITGA2, WNT10B, and CCNE1 genes." (PMID 38125763, 2023). "Beyond this, the pathway in cancer revealed that most of the genes are relative to WNT pathway (WNT7B, WNT6, WNT10B, FZD6, FZD8, and LPAR5), and among these, WNT7B, WNT10B, FZD6, FZD8, and LPAR5 belonged to the classical WNT pathway." (PMID 34122668, 2021). "The WNT signaling in our study is altered by the deregulation of APC, FZD1, FZD6, LRP6, and WNT10B, which are included by KEGG in the process of cancer proliferation." (PMID 34715892, 2021). "Our work revealed a yet unrecognized and unexpected function of Wnt10b signaling to protect cells from mitotic errors and chromosomal breaks in response to DNA replication stress, which is a major source for chromosomal instability (CIN) in human cancer." (PMID 40846632, 2025). "In this study, we showed that Wnt10b signaling acts downstream of RS, but does not impact DNA replication dynamics in cancer cells per se." (PMID 40846632, 2025). "Importantly, the replication stress–induced chromosomal breaks in these CIN+ cancer cells were also efficiently suppressed upon Wnt10b, but not Wnt3a treatment." (PMID 40846632, 2025). "Here, we show that in human cancer cells Wnt10b signaling is required upon replication stress to ensure normal microtubule dynamics from the S phase until mitosis and to prevent chromosomal breaks and mitotic errors without affecting DNA replication dynamics per se." (PMID 40846632, 2025). "Together, we conclude that inhibition of Wnt10b signaling leads to mitotic chromosome missegregation, but Wnt inhibition impacts neither DNA replication dynamics nor cell cycle progression in human cancer cells." (PMID 40846632, 2025).
infection (5 papers, 2023 to 2025). The state of being infected such as from the introduction of a foreign agent such as serum, vaccine, antigenic substance or organism. "The engineered cell line producing engineered exosome was developed by infection with lentivirus containing three cargo genes (WNT10B, FGF7, and VEGFA) in HEK-293 cells." (PMID 40521098, 2025). "In addition, through ex vivo infection of peripheral blood mononuclear cells (PBMCs) collected from healthy donors, SFTSV inhibited the transcription levels of WNT7A and WNT10B." (PMID 37882780, 2023).
adenocarcinoma (1 paper, 2012). A common cancer characterized by the presence of malignant glandular cells. "For example, WNT10B overexpression driven by an MMTV promoter was found to direct mammary gland hypermorphic development, transformation and eventually adenocarcinoma development." (PMID 23110045, 2012).
bone disorder (1 paper, 2020). "Wnt10b has recently been recognized as a clastokine, and is potentially a therapeutic target for treating bone disorders." (PMID 33013696, 2020).
degenerative diseases (1 paper, 2025). "IF regulates lipid metabolism primarily via genes including FABP4, WNT10B, PCK1, PLIN1, LEPR, and ADIPOQ, providing energy for cold adaptation, whereas PF positively influences in vivo degenerative diseases mainly through genes such as ATP5F1A, ATP5PO, SDHB, NDUFS8, SDHA, and COX5A." (PMID 40136641, 2025).
WNT10B also shares sentences with these, for which no sentence is quoted: cervical cancer (2 papers); colon cancer (2); glioblastoma (2); Abdominal obesity (1); acute lymphoblastic leukemia (1); Arthritis (1); biliary tract cancer (1); cardiac interstitial fibrosis (1); CNS tumor (1); EEC syndrome (1); ichthyosis (1); inflammatory bowel disease (1); lung adenocarcinoma (1); mental illness (1); Microdontia (1); oral cancer (1); ovarian carcinoma (1); ovarian endometrioid carcinoma (1); parasitemia (1); pilocytic astrocytoma (1); prediabetes (1); renal fibrosis (1); rheumatoid arthritis (1); secondary hyperparathyroidism (1); small cell lung carcinoma (1); spondylitis (1); Stroke (1); testis diseases (1); Theileria infection (1).